MMP1 (matrix metallopeptidase 1)
Diseases named in the same sentence as MMP1 in open-access papers (continued):
Sharing a sentence is not in itself a finding about the gene and the disease.
melanoma (continued). "Homed melanoma cells in bone showed positive expression of MMP1, the expression of which mirrors the invasiveness and the metastatic ability of the melanoma." (PMID 33498283, 2021). "We found melanoma spheroids were less invasive in matrices containing patient fibroblast secretomes with higher amounts of MMP1." (PMID 33980846, 2021). "Homing and progression of melanoma cells in the bone leads to the manifestation of osteolytic pathology via protease activation in melanoma cells, including MMP1." (PMID 33498283, 2021). "Studies on melanoma have also confirmed that CAFs promote the metastasis and drug resistance of melanoma cells by increasing the expression of MMP1 and MMP2." (PMID 33722297, 2021). "The inhibition or blockade of soluble molecules responsible for promoting metastasis in melanoma, including MMP1, MMP2, and MMP13 is another approach." (PMID 34207884, 2021). "We confirmed the patient dermal fibroblasts express and secrete varying levels of MMP1, and embedded melanoma spheroids in matrices of collagen mixed with the donor fibroblast secretome." (PMID 33980846, 2021). "ABL1 promotes melanoma invasion through STAT3-dependent MMP1 expression, while ABL2 promotes melanoma invasion by increased expression of MMP-1, MMP-3, and MT1-MMP independently of STAT3." (PMID 34022881, 2021). "The ex vivo metastasis model reflects the progressive melanoma cell activation in vivo, resulting in decreased bone mineral density and expression of MMP1-positive cells." (PMID 33498283, 2021). "We confirmed UVR-damaged fibroblasts persistently upregulate collagen-cleaving matrix metalloprotein-1 (MMP1) expression, reducing local collagen (COL1A1), and COL1A1 degradation by MMP1 decreased melanoma invasion." (PMID 33980846, 2021). "Altogether, these data demonstrate fibroblast-secreted MMP1 degrades collagen, limiting melanoma invasion." (PMID 33980846, 2021). "Accordingly, our results reveal the upregulation of the MMP1 gene in CAF cultures that is further exacerbated by direct CAF–melanoma cell co-cultures." (PMID 34298873, 2021). "Co-culturing CAFs with melanoma cells tended to empower growth factors and MMP1 production, suggesting a reciprocal dependency between CAFs and cancer cells." (PMID 34298873, 2021). "IL-1 and bFGF produced by melanoma cells represent possible mediators responsible for the expression of MMP-1, whose levels are higher in MAFs than normal fibroblasts." (PMID 34067929, 2021). "Studies have shown that inhibition of MMP-1 decreases melanoma metastasis in nude mice, whereas forced over-expression of MMP-1 in non-invasive melanoma cells induced a metastatic phenotype." (PMID 34207884, 2021). "S100A9 binds to EMMPRIN, an inducer of MMP synthesis, to regulate MMP1 expression in a melanoma cell model." (PMID 33005006, 2020). "The SFN/FB combination inhibited melanoma cell migration in vitro, MMP-1, -2, -3, and -9 production, inflammasome activation and IL-1β secretion more efficiently than each individual compound did." (PMID 32486135, 2020). "TNF-α and TGF-β secreted by macrophages synergistically increase melanoma migration in a NF-κB dependent manner through the release of MMP-1 and MT1-MMPs." (PMID 31134198, 2019). "For example, TCDD exposure of human A2058 melanoma cells induced the expression of MMP-1, MMP-2, and MMP-9, which was associated with enhanced invasive growth of melanoma cells in vitro." (PMID 31795255, 2019). "Previous findings indicate that TWIST1 promotes invasion via the upregulation of MMP1 in human melanoma cells." (PMID 30975980, 2019). "As an example of SFM-DR by CAFs, studies of the drug resistance of melanoma to chemotherapeutic agents have shown that CAFs assisted in metastasis and drug resistance by increasing the expression of IL-6, IL-8, MMP1, MMP2, and MMP972,73." (PMID 29403007, 2018).
melanoma (continued). "MMP-1 is shown to enhance type I collagen levels through skin to promote melanoma invasion, whereas PAR-1 activation leads to an increase in growth factor activation of EGFR and IGF-1." (PMID 29291033, 2017). "The migration capability of melanoma cells is enabled by thrombin- or MMP-1-mediated PAR-1 activation." (PMID 29291033, 2017). "The stable expression of the active form of MMP1 was found to promote melanoma growth through the generation of active TGF-β, an inducer of EMT21." (PMID 27324842, 2016). "MMP-1, secreted by melanoma and activated stromal cells, contributes to the progression of melanoma in two ways." (PMID 27271600, 2016). "In vitro, in melanoma cells, PL preferentially inhibited MMP-1 in an AP-1-dependent manner, which is consistent with reduced degradation of interstitial collagen, and stimulated TIMP-2, implicated in the inhibition of basement membrane remodeling." (PMID 27367679, 2016). "One study, which attempted to identify a molecular signature in human RGP and VGP melanoma cell lines, found an invasion-specific signature that was characterized by the upregulation of genes including IL-6, IL-8, and MMP-1." (PMID 25798946, 2015). "MMP-1 is thought to facilitate melanoma invasion by degrading type I collagen within the skin, while PAR-1 activation leads to increased activation of growth factors: FGFR-2 and IGF-1." (PMID 26573921, 2015). "Several MMPs, including MMP-1, -2, -3, -7, -9, -13, -14, -15, -16 as well as uPA have been demonstrated to play a crucial role in human melanoma progression, invasion and metastasis." (PMID 26197340, 2015). "In chondrosarcoma, esophageal cancer and melanoma, patients with increased levels of MMP-1 expression are correlated with a worse outcome regarding tumor invasion and metastasis." (PMID 24505369, 2014). "For example, in melanoma cells, Twist binding to the MMP-1 promoter was found to increase expression of MMP-116." (PMID 25339983, 2013). "Nuclear Gal-3 contributes to melanoma metastasis by regulating multiple genes such as VE-cadherin, MMP-1, MMP-2, interleukin 8 (IL-8), and autotaxin." (PMID 24069584, 2013). "Human MMP-13 and MMP-1 are also linked to cutaneous malignancies, such as SCC, and melanoma, which involve inflammation, stromal cell activation, and angiogenesis in the tumor micro-environment." (PMID 22880047, 2012). "Type I collagenase and PAR-1 activating functions of MMP-1 (matrix metalloproteinase-1) are required for melanoma progression." (PMID 20936153, 2010). "In conclusion, our results show that elastin degradation products are important modulators of in vivo melanoma growth and invasion through Mcol-A (MMP-1) expression." (PMID 20959825, 2010). "Melanoma and tumor stromal cells express several MMPs, including MMP-1, -2, -3, -7, -9, -14, -15, -16, as well as tissue inhibitors of MMPs such as TIMP-1, -2, and -3." (PMID 20631829, 2010). "All MMPs upregulated in Hm cells were previously reported to be produced in melanoma, in particular MMP1 and -9." (PMID 20667128, 2010). "In our model, EDPs induced B16F1 invasion through Mcol-A expression, reinforcing the fact that MMP-1 is a crucial protease for melanoma invasion." (PMID 20959825, 2010). "In melanomas, higher levels of MMP-1, MMP-2, MMP-9, and MMP-14 have been observed in the more invasive and metastatic tumors." (PMID 20843370, 2010). "Our melanoma invasion signature is associated with upregulation of critical NF-κB effectors including CXCL1, FMN2, MMP1, IL-8, IGFBP3 which have been implicated in the regulation of tumor cell proliferation, motility, migration, and/or invasion." (PMID 17611626, 2007). "Increased MMP-1 expression was found to be associated with more aggressive MMs that have no spontaneous regression, contrasting with some melanoma types that exhibit such a feature." (PMID 39063046, 2024). "In sum, our findings suggest that MMP1 may have an active pathobiological role in gray horse melanoma similar to what is observed in hMM." (PMID 38891088, 2024).
melanoma (continued). "Interestingly, comparative MMP1 RT-qPCR from primary melanoma cells (DOLmc) and normal skin tissue originating from the same individual revealed similar MMP1 transcription levels." (PMID 38891088, 2024). "Moreover, in human WM115 and WM266-4 melanoma cells, the combination of SFN (5 and 10 μM) and Fernblock® XP (FB) hindered melanoma cell migration in vitro and curbed the production of MMP-1, -2, -3, and -9, inflammasome activation, and IL-1β secretion." (PMID 38671854, 2024). "Experimental studies in mice have revealed that reduced MMP-1 expression in a melanoma cell line results in a decreased ability of tumor cells to metastasize and, on the contrary, its introduction into noninvasive melanoma cells induces a metastatic phenotype in vivo." (PMID 39769318, 2024). "MMP1 staining consistently yielded a cytoplasmic signal in 100% of the cultured melanoma cells." (PMID 38891088, 2024). "For instance, the study found that in melanoma with partial regression, MMP-1 and MMP-11 expressions were significantly lower in the regressed component compared to the non-regressed component, suggesting that MMP activity is closely linked to tumor aggressiveness and regression dynamics." (PMID 39200315, 2024). "MMP-9, as well as MMP-1, is a pro-angiogenesis factor, and they could both be prognostic biomarkers for melanoma." (PMID 36980564, 2023). "In melanoma, upregulation of matrix metalloproteinases (MMPs) is associated with migration of the tumor, and upon treatment of B16F10 cells with NPC-402, it dose-dependently downregulates the expression of MMP1 and MMP9 compared to untreated." (PMID 35982963, 2022). "Similarly, the expression of MMP-1 was reported to promote anchorage-independent growth and melanoma growth through the generation of active transforming growth factor beta." (PMID 35267541, 2022). "Although response to MMP1-related immunotherapy was reported in melanoma (all group, P = 0.0458; MAPKi group, P = 0.0355) and urothelial cancer (all group, P = 0.0168; smoking group, P = 0.0132), its correlation or lack of in HCC has not been reported in any cohort studies thus far." (PMID 35948625, 2022). "Also, BMP‐2 and ‐4 stimulation of primary human fibroblast led to MMP‐1, ‐2, ‐3, and ‐13 upregulation which was suggested to be a mechanism in melanoma invasion." (PMID 33629769, 2021). "Conversely, inhibiting ECM degradation and MMP1 expression restored melanoma invasion." (PMID 33980846, 2021). "Additionally, MMP-1, known as pro-collagenase-1, is overexpressed in BRAF-mutated melanoma and contributes to melanoma invasion and growth by activating the ERK pathway." (PMID 33833342, 2021). "Consistent with a higher MMP1 expression, the noCSD-UV secretome significantly decreased melanoma invasion compared to the noCSD secretome (p = 0.001), and importantly, Batimastat restored melanoma cell invasion (p = 0.01)." (PMID 33980846, 2021). "Here, the authors report that UVR-damaged dermal fibroblasts upregulate MMP1 to degrade collagen which inhibits melanoma invasion and that aged primary melanomas in skin with degraded collagen have a better prognosis, while new collagen synthesis restores invasion and leads to death." (PMID 33980846, 2021). "Similarly, ABL kinases drive melanoma cell invasion by inducing expression of matrix metalloproteinases MMP-1, MMP-3, and MT1-MMP." (PMID 34022881, 2021). "We also investigated the correlation of the seven prognostic-associated TBCs between MMP-related genes (MMP2, MMP9, MMP7, MMP14, BSG, EGFR, MMP1, MMP3) and EMT-associated genes (TWIST1, VIM, CDH2, ACTA2, ZEB1), which also indicated a central role of TBCs in melanoma." (PMID 33194704, 2020). "Melanoma associated fibroblast are also able to remodel the ECM by MMP-1, MMP-2, MMP-13, and MT1-MMP (MMP-14) secretion, which could influence the motility and invasiveness of melanoma cells." (PMID 32984031, 2020).
melanoma (continued). "Notably, MMP1 was identified to be a novel downstream target of TWIST1, implicated in facilitating invasion in human melanoma cells." (PMID 27324842, 2016). "Specifically, PL promotes expression of TGF-β in non-irradiated or UV-irradiated fibroblasts but inhibits TGF-β in melanoma cells, which may be responsible for the observed inhibition of MMP-1 expression induced by in these cells." (PMID 27367679, 2016). "Furthermore, a MMP1/PAR1 axis was found to facilitate melanoma invasion, tumour growth and metastasis." (PMID 27324842, 2016). "ETS1 also regulates genes involved in melanoma cell invasiveness: MMP1, MMP3 and integrin-β3." (PMID 26885752, 2016). "Overexpression of Twist1 in melanoma augmented melanoma migration and invasion via MMP-1." (PMID 25868853, 2015). "Collagenase-1 (MMP-1) has been shown to be important in melanoma development and could be activated by the plasminogen system." (PMID 20959825, 2010). "It has already been suggested that MMP-1 could be important in melanoma development through its secretion by melanoma but also by stromal cells and, recently, it was shown that shRNA-driven MMP-1 knockdown inhibited metastasis formation in a xenograft model." (PMID 20959825, 2010). "Human melanoma invasion involved MMP-1, MMP-2, MMP-9 and MT1-MMP." (PMID 20959825, 2010). "Moreover, re-invigoration of exhausted T cells and inhibition of UVR-induced MMP-1 production highlight mechanisms whereby the peptide may subvert progression of skin cancers, particularly melanoma." (PMID 37474630, 2023). "Moreover, MMP-1 activates PAR1, which is associated with invasiveness in melanoma." (PMID 36678726, 2022). "Furthermore, the expression level of MMP-1 was attenuated in Olig2 knockdown of melanoma cells." (PMID 33833342, 2021). "However, there is also evidence that MMP-1-mediated PARs activation exists in melanoma cells." (PMID 26573921, 2015). "Finally, MMP-1 was shown to be expressed during the invasion of malignant melanomas." (PMID 20959825, 2010). "Among the genes downregulated by melanoma-derived SPN, MMP-1, MMP-3, and MMP-12 showed similar expression patterns in both NHFs and CAFs." (PMID 40869222, 2025). "Immunomodulatory CAFs (iCAFs) displayed high expression of MMP1, MMP3, IL6, CXCL8, and IDO1, and included CAFs from melanomas, 1 SCC, and 1 BCC." (PMID 38525245, 2024). "Prominent MMPs, including MMP-1, MMP-2, MMP-3, MMP-9, MMP-13, and MMP-14, have been shown to significantly contribute to the development of melanoma." (PMID 39769318, 2024). "A375 melanoma cells were stimulated with LL-37, and the mRNA expression of CXCL5, IL23A, MMP1, and MMP9 were evaluated in vitro." (PMID 36980564, 2023). "In addition to MMP1/3/9 only being variably expressed across melanoma cell lines, type I collagen degradation activity (associated with MMP1) and MMP3 levels are not elevated in UV-exposed, wrinkle-bearing skin, raising the question of which MMPs are more relevant for photoaging." (PMID 35316219, 2022). "ADAM-9 also induces cell signalling leading to increased secretion of the proteolytic enzymes MMP-1 and MMP-2 in fibroblasts and MMP-2 in melanoma cells." (PMID 34067929, 2021). "We previously reported that the Thai Herbal HRF extracts protected against UVA-induced MMP-1 in keratinocyte HaCaT cells and melanogenesis in B16F10 melanoma cells through activating Nrf2-dependent antioxidant defenses." (PMID 33912060, 2021). "All others demonstrate an increased expression in melanoma development, some even strongly like PMP2 (5.7-fold), TNC (10.2-fold), MMP1 (65.6-fold), and CDH2 (10.2-fold)." (PMID 34439267, 2021). "We further verified that Olig2 influences the expression of MMP-1, another MMP that is important for invasion and growth of melanoma." (PMID 33833342, 2021). "ATX down-regulated MMP-1, MMP-2, and MMP-9, resulting in the inhibition of migration and invasion of melanoma cells in a dose-dependent manner from 5 – 125 μg/ml for 24 h." (PMID 32711429, 2020).
melanoma (continued). "TAP-nanoemulsion triggered apoptosis of human malignant melanoma in the lung by inhibiting Bcl-2, cyclins D1 and E, NF-κB, ERK, MEK, and MMP-1 and MMP-9 and increasing cleaved caspase-9 and caspase-3, ATM, and p21." (PMID 32908627, 2020). "Matrix metalloproteinases such as MMP-1, -2, -3, -8, -9, -10, -13, -15, -16, and -26 can facilitate tumor growth, invasion, and angiogenesis in BCC, SCC and melanomas." (PMID 31134198, 2019). "Melanoma cells express a number of various types of MMPs such as MMP-1, MMP-2, and MT1-MMP which have essential parts in melanoma vasculogenic mimicry formation and MMP-13 which promotes invasion and metastasis." (PMID 30800067, 2019). "MMP1, MMP2 and MMP3 are known to be essential proteases for both the growth and metastatic spread of melanoma tumors." (PMID 28146421, 2017). "Increased expression of MMP-1, MT1-MMP, and MMP-2 have been correlated with increased invasion and metastasis of human melanoma." (PMID 25798946, 2015). "MMP-1 up-regulation by EDP has been described in both normal and tumor cells, such as endothelial cells, fibroblasts, melanoma and fibrosarcoma." (PMID 26086247, 2015). "Proteinase-activated receptor 1 (PAR1) activated by several proteinases including thrombin and matrix metalloproteinase-1 (MMP-1) promotes cell transformation, tumor metastasis, and angiogenesis in a variety of cancers including prostate cancer and melanoma." (PMID 25723737, 2015). "Various types of MMPs affect melanoma metastasis by degrading ECM; MMP-1, MMP-2, and MT1-MMP have essential parts in melanoma VM formation." (PMID 25749207, 2015). "Thereafter, increased mRNA levels of MMPs were reported in TCDD-treated human cells, such as, MMP1 in keratinocytes and melanoma cells, MMP2 in melanoma cells, MMP3 and MMP7 in endometrial cells, and MMP9 in prostate cancer cells and melanoma cells." (PMID 16704738, 2006). "In contrast to melanoma cell lines, M2 macrophages stimulated by LL-37 in vitro significantly increased their expression and secretion of MMP-1, but not MMP-9 expression." (PMID 36980564, 2023). "Correctively, LL-37-induced CXCL5, IL-23p19, MMP-1 and MMP-9 could promote angiogenetic activity in melanoma tumor microenvironment, leading to the local invasion of melanoma which contributes to T stage in melanoma patients." (PMID 36980564, 2023). "Combined with re-invigoration of exhausted CD4+ T cells, inhibition of UVR-induced MMP-1 release and suppression of B16F10 melanoma metastases, IK14800 offers an opportunity to gain further insight into mechanisms underlying the development and progression of skin cancers." (PMID 37474630, 2023). "Correctively, LL-37-induced CXCL5, IL-23p19, MMP-1 and MMP-9 could promote angiogenetic activity in melanoma, leading to the local invasion of melanoma which contribute to T stage in melanoma patients." (PMID 36980564, 2023). "Likewise, the insertion of a G at −1607 bp at MMP-1 promoter forms the consensus sequence 5′-AAGGAT-3′ instead of 5′-AAGAT-3′, augmenting the Ets transcription factor link and MMP-1 transcription in melanoma cells." (PMID 38069210, 2023). "Moreover, the observation that SFN and FB exert a synergistic inhibitory effect on the secretion of MMP-1, -2 and-3 further corroborates the potential use of the SFN/FB combination for the prevention of invasion and metastasis during melanoma progression." (PMID 32486135, 2020). "Vitamin D significantly inhibited MMP-1 and MMP-1 protein levels in melanoma cells." (PMID 32150881, 2020). "Collagenases, MMP-1, MMP-8, and MMP-13, are the dominant extracellular proteinases with the ability to cleave native fibrillar collagen types I, II, III, and V. As they can degrade dermal collagen, they are particularly relevant in melanoma." (PMID 27271600, 2016). "In melanoma tissue, MMP1 expression was not restricted to glandular cells." (PMID 38891088, 2024).